MIR4635 (microRNA 4635)
Synonyms: hsa-mir-4635
Gene: MicroRNA gene on chromosome 5 (1,062,896 to 1,062,974, reverse strand). Ensembl gene ENSG00000263834.
Homologues: Orthologues: chimpanzee MIR4635 (100% identical).